IL6 (interleukin 6)
Diseases named in the same sentence as IL6 in open-access papers (continued):
Sharing a sentence is not in itself a finding about the gene and the disease.
joint disease (continued). "Under the influence of joint disease, many cytokines and collagen turnover biomarkers accumulate in synovial fluid, including COMP, CC-chemokine ligand 5 (CCL5), matrix metalloproteinase-1 (MMP-1), MMP-3 and MMP-18, as well as tumor necrosis factor-alpha (TNF-α), interleukin-6 (IL-6) and IL-8." (PMID 36835530, 2023). "However, since hs-CRP and IL-6 serum levels also correlated with the orthopaedic joint score (OJS), it is highly likely that the pathophysiology of inflammation was multifactorial in our patient cohort, with blood-induced joint disease playing an additional role." (PMID 32430703, 2020). "Patients with clinically significant arthropathy (n = 22), as defined by an OJS > 4, were older (Online Resource 7B) and had higher IL-6 serum levels (3.6 (1.9–6.1) vs. 1.8 (1.0–3.4) ng/L, median (IQR); P < 0.05) than patients without clinically significant arthropathy (n = 21)." (PMID 32430703, 2020).
psoriatic arthritis (41 papers, 2005 to 2026). Joint inflammation associated with psoriasis. "Ninety pediatric participants (JIA, CD, psoriatic arthritis, healthy controls) underwent serum cytokine profiling (IL-1α, IL-1β, IL-36α, IL-37, IL-6, IL-18, IL-27, IL-31) at baseline and 12 months." (PMID 42196228, 2026). "Currently, treatment with interleukin-6 inhibitors is expected to be effective and suppress the joint destruction in patients with psoriatic arthritis; however, evidence regarding their efficacy is limited to a few reports." (PMID 36324145, 2022). "We experienced a case of psoriatic arthritis, in which anti-interleukin-6 treatment repaired a bone cyst in the lateral epicondyle of the humerus and enthesitis of the distal interphalangeal joints." (PMID 36324145, 2022). "For example, a phase III randomized clinical trial of apremilast found a significant decrease in TNF-α, IL-6, and IL-8 levels in psoriatic arthritis patients after 24 weeks of BID dosing." (PMID 33052879, 2020). "We found that signs of systemic inflammation were present in most of the patients, correlated with the severity of the disease, and pointed to IL-6 involvement in the pathogenesis of psoriatic arthritis." (PMID 28790368, 2017). "Taken together, signs of systemic inflammation are present in most of the patients, correlate with the severity of the disease, and point to IL-6 involvement in the pathogenesis of psoriatic arthritis." (PMID 28790368, 2017). "Moreover, high PLR combined with increased serum values of IL-6 and nail involvement was recently proven to be a subclinical indicator of psoriatic arthritis." (PMID 39064032, 2024). "On the other hand, the use of new IL-6 inhibitors such as clazakizumab, a monoclonal antibody with high affinity and specificity for IL-6, could be more promising for psoriatic arthritis (PsA)." (PMID 36901778, 2023). "Both conventional and unconventional IL-17A+ CD8+ T-cells were able to induce pro-inflammatory IL-6 and IL-8 production by synovial fibroblasts from patients with psoriatic arthritis, which was reduced upon addition of anti-TNFα and anti-IL-17A neutralizing antibodies." (PMID 37367825, 2023). "Anti-interleukin-6 treatment may address the unmet needs of patients with psoriatic arthritis who are resistant or intolerant to antitumor necrosis factor treatment, with rapidly destructive large joints but with well-managed skin manifestations." (PMID 36324145, 2022). "However, the IL-6 blockade strategy shows few consistent beneficial effects when used to treat plaque-type psoriasis and psoriatic arthritis (PsA)." (PMID 31659208, 2019). "Several studies have demonstrated the efficacy of inhibitors of IL-6, IL-17, and TNF-α in the management of chronic plaque psoriasis and psoriatic arthritis." (PMID 39411067, 2024). "The pathogenesis of psoriatic arthritis is related to the innate and adaptive immune response involving different proinflammatory cytokine, including TNF, IL-1β, IL-6, IL-22, IL-23, IL-17A, and IL-18." (PMID 36297574, 2022). "In patients with psoriatic arthritis, apremilast has been shown to reduce plasma levels of TNF- α, IL-6, and other pro-inflammatory cytokines and chemokines." (PMID 26370839, 2015). "IL-6 inhibition did not provide therapeutic benefits in psoriatic arthritis, ankylosing spondylitis and certain connective tissue diseases." (PMID 36260501, 2022). "In this context, current evidence indicates that IL-6 blockade does not seem to be effective in psoriatic arthritis (PsA) or axial spondyloarthritis (axSpA)." (PMID 36260501, 2022). "In contrast, MTX, an anti-inflammatory drug that is widely used to treat patients with RA and psoriatic arthritis, did not reduce inflammatory markers, such as interleukin-1, interleukin-6, C-reactive protein, or cardiovascular events in the CIRT trail." (PMID 33416495, 2021).
Ascites (40 papers, 2007 to 2026). Accumulation of fluid in the peritoneal cavity (between the layers of the peritoneum that lines the abdomen). "Elevated IL-6 was associated with male sex, hepatomegaly, ascites, cherry angiomata, low albumin, endocrinopathy, reduced Diffusing Capacity of the Lung for Carbon Monoxide (DLCO), mixed sclerotic/ lytic bone lesions, and higher light chain values." (PMID 40646134, 2025). "IL‐6 and IL‐8 reflected an increased risk of ascites when analyzed in the continuous model (per 1‐SD augment) (p < .01)." (PMID 38411379, 2024). "OC-associated ascites showed an inhibitory effect on the production of the cytokines IL-6, IL-12p40 and TNFα in response to R848- and LPS-mediated activation." (PMID 28410380, 2017). "Multivariable analysis of significant, immune factors revealed independent association of IL-6 with the ascites development, as well as the poor 90 day prognosis." (PMID 26107937, 2015). "Although, our data suggest that IL-6 levels in ascites are associated with shorter progression-free survival, the precise underlying molecular mechanisms responsible for these findings remain to be established." (PMID 21619709, 2011). "In other studies, the presence of inflammatory markers like IL-6 in the blood was correlated with disease severity in patients with ascites." (PMID 38797850, 2024). "At the end of this study, we evaluated the predictive value of 12 cytokines for AP patients with ascites, and IL‐6, IL‐8, and IL‐10 still had good value." (PMID 38411379, 2024). "It has also been proposed that IL-6 is a major mediator of ascites formation based on its involvement in angiogenesis and hyperpermeability." (PMID 32138790, 2020). "Concerning levels of IL-6 in ascites, former studies described a correlation of ascitic IL-6 with the diagnosis of SBP." (PMID 32899730, 2020). "In dogs with SP, the concentrations of glucose, cfDNA, nucleosomes, PCT, CCL2, IL-6, IL-10, and KC-like were significantly different between blood and peritoneal effusion." (PMID 31316998, 2019). "When the association between the expression of IL-6 and the history of ascites was evaluated, a direct significant correlation was found between the IL-6 expression and post-treatment ascites formation (p:0.034, correlation coefficient = 0.214)." (PMID 26282935, 2015). "Mean IL-6 expression scores in the ascites group (3.59 ± 0.19) were significantly higher than those in the non-ascites group (2.91 ± 0.24, p:0.039)." (PMID 26282935, 2015). "In multivariate analysis, however, IL-6 was identified as an independent predictive factor for the development of post-treatment ascites (p:0.033)." (PMID 26282935, 2015). "The predictive value of IL-6 expression with regard to the development of post-treatment ascites was further evaluated employing logistic regression analysis." (PMID 26282935, 2015). "IL-6 targeting for the prevention of the ascites development is a potential avenue for further investigation." (PMID 26282935, 2015). "Univariate test revealed the significance of the IL-6 expression for predicting the development of post-treatment ascites (HR = 0.39; 95 % CI, 0.16-0.94; p 0.036)." (PMID 26282935, 2015). "It has also been demonstrated that cytokine blockade with anti-TNF-α monoclonal antibody can decrease the incidence of BT in cirrhotic rats with ascites, and the integrity of intestinal barrier can be preserved in the IL-6 knockout mice." (PMID 25171482, 2014). "Consistent with a previous study, IL-6 was the most abundant factors in ascites." (PMID 35875098, 2022). "The concentration of IL-6 in this group was significantly higher in ascites than in blood serum." (PMID 34572929, 2021). "IL-6 is further increased in serum of patients with ascites." (PMID 28661458, 2017). "In addition, another theory is that substances such as VEGF that raise capillary permeability and some inflammatory cytokines including interleukin (IL)-1β, IL-6, and IL-8 are possible etiologies of ascites and hydrothorax formation." (PMID 27160723, 2016).
Ascites (continued). "Interestingly, the predictive value of IL-6 for the development of post-treatment ascites was observed in the present study." (PMID 26282935, 2015). "The mean concentration of IL-6 and IL-8 was determined by ELISA in the 39 ascites samples." (PMID 21619709, 2011). "Because of the high levels of IL-6 and IL-8 found in ascites and the prosurvival activity of ascites, we hypothesized that IL6 and IL-8 could impact on progression-free survival." (PMID 21619709, 2011). "The IL-1α, IL-6, and TNF-α levels were found to be higher in the plasma and ascites of cirrhotic patients compared to those in plasma from healthy individuals." (PMID 40149656, 2025). "Pleural and peritoneal effusions from patients with PEL generally contain high concentrations of viral IL-6 (vIL-6), as well as human IL-6 (hIL-6) and IL-10." (PMID 39518131, 2024). "IL-6 can induce vascular endothelial growth factor (VEGF) production and pulmonary vascular permeability, and the degree of ascites was found to be correlated with serum VEGF levels in cats with FIP." (PMID 31835559, 2019). "Additionally, IL-6 levels in both ascites and serum were significantly higher in patients with SBP (ascites P < 0.001, serum P = 0.036)." (PMID 38962151, 2024). "Furthermore, previous studies showed deregulation of different mediators, illustrated by the upregulation of pro-inflammatory cytokines such as IL1β, IL6, TNFα, MIP1α, RANTES, and IFNγ in peritoneal effusions and serum samples of FIP clinical cases." (PMID 28388950, 2017). "Subgroup analysis did not indicate a statistically significant difference in mean IL-6 expression scores between patients who had ascites at the time of diagnosis (3.56 ± 0.22) and those without ascites (3.11 ± 0.21, p:0.154)." (PMID 26282935, 2015). "The association between dietary fiber intake and interleukin (IL)-1β, IL-6, tumor necrosis factor-α (TNF-α), monocyte chemoattractant protein-1 (MCP-1), B-cell activating factor (BAFF), and plasminogen activator inhibitor-1 (PAI-1) levels in serum and peritoneal effusion." (PMID 40735439, 2025). "Collectively, our data demonstrate that the progression of patients from outpatients with ascites to patients hospitalised with AD/ACLF is accompanied by an increase in bioavailable PGE2, reduced monocyte HLA-DR expression, and reduced monocyte TNFα/IL6 production." (PMID 34825153, 2021). "The presence of ascites did not correlate with higher levels of serum IL6 (p = 0.09)." (PMID 32042020, 2020). "On the other hand, the comparison of mean IL-6 expression scores between patients who did and did not develop ascites after treatment (3.85 ± 0.26 and 3.00 ± 0.18, respectively) revealed significantly higher levels of IL-6 expression in the ascites positive group (p:0.007)." (PMID 26282935, 2015). "IL-6 may be cleared rapidly from the circulation and consequently serum levels may not correlate with ascites levels." (PMID 21619709, 2011). "We conclude that levels of IL-10 found in OC-associated ascites positively correlate with the inhibitory properties of ascites on the TLR-mediated up-regulation of the co-stimulatory molecule CD86, as well as the production of the cytokines IL-6 and IL-12p40 but not TNFα." (PMID 28410380, 2017). "However, in a study of several potential biomarkers in dogs, KC-like did not discriminate between septic peritonitis and nonseptic ascites, as did blood concentrations of CCL2 and peritoneal effusion concentrations of CCL2, IL-6, IL-10 and lactate." (PMID 39272157, 2024).
Immunodeficiency (40 papers, 2013 to 2025). Failure of the immune system to protect the body adequately from infection, due to the absence or insufficiency of some component process or substance. "Immunodeficiency, another important aspect of an underlying disease, was also analyzed with the level of IL-6." (PMID 33746945, 2021). "Cytokines and immune deficiency can still be considered in this extension, as the secretion of IL-6, which supports initiation and progress of PCa, has been increased in subjects with MGUS in previous studies." (PMID 34588555, 2021). "Nutritional intervention increases IL-6 in both wasted and severely wasted, but it is reduced with good nutrition, which is in line with research that states undernutrition, even in the mildest form causes immunodeficiency." (PMID 38434639, 2023). "Here, we identify a patient with a causative homozygous mutation in IL6ST, encoding the human cytokine receptor subunit GP130, presenting with immunodeficiency and skeletal abnormalities including craniosynostosis, and demonstrate associated defects in IL-6, IL-11, IL-27, and OSM signaling." (PMID 28747427, 2017). "In STAT3-HIES, immunodeficiency is primarily due to defective IL-6 signaling, which plays a crucial role in Th17 cell differentiation." (PMID 40491905, 2025). "The latest IUIS classification has redefined DOCK8 deficiency as a combined immunodeficiency, and other genes like ZNF341 and components of the IL-6 pathway (IL6ST, IL6R) can cause HIES-like phenotypes." (PMID 41458089, 2025). "Immunodeficiency subjects with low level of production of cytokine IL-6 showed a better disease outcome; hence, the evidence highlights a controversial role of B cells in disease progression." (PMID 39063987, 2024). "Immunodeficiency induced by CYP treatment has been associated with a decrease in the production of cytokines such as TNF-α and IL-6." (PMID 38474724, 2024). "It has also been reported that elderly individuals have higher levels of IL-6 after acute infection and that immunodeficiency in elderly individuals affects innate immunity." (PMID 37095536, 2023). "Individuals with ESRD have serious immune deficiencies and accumulate a large amount of uremic toxins, which stimulate the body to produce inflammatory factors such as TNF-α, IL-6, and IL-1β, leading to sustained microinflammation reaction." (PMID 37550622, 2023). "Fittingly, humans with bi-allelic LOF mutation in gp130 that affects both IL11 and IL6 signalling present with combined immunodeficiency (IL6/OSM effect) and craniosynostosis (IL11 effect)." (PMID 38054591, 2023). "Multiple linear regression analysis showed that the presence of immunodeficiency was a factor that significantly affected serum IL-6 and age was a factor that significantly affected IL-28A/IFN-λ2." (PMID 35361913, 2022). "FGF23 can provoke cardiotoxicity via left ventricular hypertrophy, immunodeficiency via suppression of neutrophil migration, and inflammation via interleukin 6 (IL-6) production." (PMID 33832448, 2021). "Suggested potential etiological factors for CD are lymphoid-hamartomatous hyperplasia, autoimmune phenomena, immunodeficiency, chronic low-grade inflammation, and excess production of interleukin-6 (IL-6)." (PMID 28501028, 2017). "The results showed that the sodium hyaluronate health drink could improve thymus atrophy, repair spleen cell damage, promote the release of IL-2, IL-6 and TNF-α in serum, restore immune deficiency, and enhance immune function." (PMID 38540831, 2024). "Subtype 1 had upregulated PI3K/Akt signaling, MAPK signaling, focal adhesion, ECM-receptor interaction pathways, as well as immune response-related pathways, including cytokine-cytokine receptor interaction, IL-6 signaling, inflammatory response, immunodeficiency, and immunological rejection." (PMID 38245587, 2024).
Immunodeficiency (continued). "However, our data still suggest a substantial innate immune deficiency in PWH on cART compared with the majority of the participants still having LPS-induced IFN-α and IFN-γ and Poly I:C-iduced IL-6 and TNF-α concentrations below the reference intervals." (PMID 36059528, 2022). "Our findings indicate that more severe immunodeficiency and higher mycobacterial antigen load (extra-pulmonary disease and shorter interval between ATT and ART initiation) along with higher levels of IL-6 and CRP prior to ART initiation are strongly associated with paradoxical TB-IRIS." (PMID 23691062, 2013). "Anti-IL-6 therapy may be beneficial for DOCK8-deficient subjects who prove unresponsive to conventional antiviral chemotherapies, indicating a prospective avenue for clinical management of this immunodeficiency." (PMID 39044832, 2024). "Also, as shown in the experiment using the immunodeficiency mouse model, we found that HLA-G expression could be modulated by hypoxia and by IL-6 production." (PMID 38877399, 2024). "Interestingly, our study illustrated that CCNA2 could enhance the development of ccRCC via several immune-related signals, including immunodeficiency, natural killer cell-mediated cytotoxicity pathway, and IL6-JAK-STAT3 pathways." (PMID 35401923, 2022). "To determine whether the viral complementation of immunodeficiency was unique to HOIL-1, we latently infected IL-6, Caspase-1-deficient and Caspase-1;Caspase-11-double-deficient mice, which survive MHV68 infection but are all highly susceptible to Listeria infection." (PMID 25599590, 2015). "MHV68 latency also protected IL-6, Caspase-1 and Caspase-1;Caspase-11 deficient mice from Listeria-induced lethality, indicating that the ability of latent infection to complement a genetic immunodeficiency is not restricted to mutation of Hoil-1." (PMID 25599590, 2015). "Elevated systemic levels of pro-inflammatory cytokines, such as IL-1, IL-6, and TNF-α, disrupt lymphocyte proliferation, differentiation, and effector responses, thereby driving progressive immunodeficiency." (PMID 40444244, 2025). "There are potential biomarkers emerging for immunodeficiency, chronic inflammation (CD4+, CD8+, T cells, B cells, IgA, IgG2, hyper IgM, IL-6 and IL-8) and steroid therapy use." (PMID 39812834, 2025). "Nevertheless, biochemistry data, such as IL-6, were collected in the following sessions in the course of ILD and SARS in Taiwan to facilitate the monitoring of drug use in immunodeficiency diseases." (PMID 35740313, 2022). "This suggests that HHV8 replication due to immunodeficiency was the primary pathogenesis of HIV-MCD in these cases, resulting in a vicious cycle of hIL6 production being blocked by the inhibition of IL6 signal transmission following the administration of tocilizumab." (PMID 24438824, 2014). "Despite having slightly larger lesion sizes and bacterial burden during infection, CGD mice did not have significant differences in their mRNA levels for IL-1ß, IL-6, or IL-17A, consistent with their immunodeficiency reflecting a defect in neutrophil function rather than cytokine production." (PMID 25909449, 2015). "Murine TNF-α, IL-1β, and IL-6 in the negative control group (NSG mice without AAV-PCSK9 injection) were below the ELISA detection threshold (1–5 pg/mL), consistent with NSG mice's severe immunodeficiency, which limits murine immune responses." (PMID 40237461, 2025).